TTR (transthyretin)
Diseases named in the same sentence as TTR in open-access papers (continued):
Sharing a sentence is not in itself a finding about the gene and the disease.
amyloidosis (continued). "The FDA and the EMA approval of nusinersen (Spinraza) for spinal muscular atrophy in 2016 and the FDA and the EMA approval of patisiran (Onpattro) for hereditary transthyretin-mediated amyloidosis in 2018 demonstrated the clinical efficacy of RNA therapeutics and accelerated research in this field." (PMID 39596348, 2024). "Hereditary transthyretin amyloidosis (hATTR) with polyneuropathy (formerly known as Familial Amyloid Polyneuropathy (FAP)) is an endemic amyloidosis involving the harmful aggregation of proteins, most commonly transthyretin (TTR) but sometimes also apolipoprotein A-1 or gelsolin." (PMID 38927056, 2024). "The authors ultimately postulate that fibrils with fragmented TTR might be the standard amyloid composition in ATTRv amyloidosis." (PMID 38907862, 2024). "The structural changes induced by a three-residue negative register shift of a β-strand in human transthyretin, a tetrameric plasma protein associated with amyloidosis, are directly linked to amyloid fibril formation." (PMID 39068227, 2024). "Therefore, systemic amyloidosis with transthyretin (TTR) protein is the most common type of amyloidosis that induces cardiomyopathy, leading to heart failure (HF) and mortality worldwide." (PMID 39796004, 2024). "Here, we demonstrate a streamlined in situ amyloid peptide spatial mapping by Matrix Assisted Laser Desorption Ionization–Mass Spectrometry Imaging (MALDI-MSI) combined with Trapped Ion Mobility Spectrometry for potential transthyretin (ATTR) amyloidosis subtyping." (PMID 38961380, 2024). "Biopsy in patients with CTS for amyloid detection, especially in elderly patients with bilateral symptoms and trigger finger, may be useful for the early diagnosis of amyloidosis, primarily due to transthyretin." (PMID 39124595, 2024). "However, genetic testing has now become low-cost (and for TTR amyloidosis can be free), non-invasive, and is now widely used in medicine." (PMID 38541013, 2024). "ATTR may further be subclassified into hereditary transthyretin amyloidosis (ATTRv) and wild-type transthyretin amyloidosis (ATTRwt)." (PMID 39519011, 2024). "As TTR is routinely cocrystallized in the presence of ligands of interest, our function can be a good method to use that data in other ways than the traditional assessment of binding mode and allow an initial selection of the better anti-TTR amyloidosis candidates." (PMID 38398647, 2024). "In 2021, promising results were published from a phase I, in vivo, CRISPR-Cas9-based gene-editing clinical trial in transthyretin (TTR) amyloidosis, in which progressive potentially fatal damage occurs due to the deposition of misfolded TTR protein in nerves and the heart." (PMID 39062641, 2024). "Analysis of the relevant literature suggests that this may be due to an increase in protein content from the accumulation of transthyretin protein, which is produced by the choroid plexus and resistant to degradation due to amyloidosis." (PMID 39314866, 2024). "However, it was not until 2018 that RNA-based therapies truly entered the mainstream with the approval of patisiran, an siRNA-based drug that targets transthyretin (TTR) amyloidosis, a rare genetic disorder." (PMID 39598489, 2024). "In 2018, patisiran, the first siRNA drug approved by the U.S. Food and Drug Administration (FDA), was found to target transthyretin (TTR) messenger RNA in the liver to fight hereditary transthyretin amyloidosis, highlighting the potential of RNAi-based therapeutics for the treatment of diseases." (PMID 39065635, 2024). "This is analogous to the situation in ATTR amyloidosis, where highly destabilized transthyretin variants are not exported from the liver due to stringent quality control within hepatocytes." (PMID 39598451, 2024). "We sought to determine whether carriers of TTR V142I of AA ancestry with heart failure or arrhythmia had extra-cardiac manifestations of amyloidosis, which could help suggest the diagnosis of amyloidosis." (PMID 38541013, 2024).
amyloidosis (continued). "Two forms are mainly reported: light chain (AL) and transthyretin (ATTR) amyloidosis." (PMID 38803660, 2024). "The Transthyretin Amyloidosis Outcomes Survey (THAOS) is an ongoing, global, longitudinal, observational survey of patients with ATTR amyloidosis, including both hereditary and wild-type disease, and asymptomatic carriers with TTR variants." (PMID 38241252, 2024). "However, the clinical treatment of transthyretin-related amyloidosis still presents several challenges, urging the development of new and improved therapeutics." (PMID 39337457, 2024). "Indeed, the recent introduction of tafamidis into therapy represents a major breakthrough for the treatment of TTR-related amyloidosis." (PMID 39337457, 2024). "In addition, TTR-7R increased cultured cell viability from 62% to 89%, scavenged amyloid plaques in AD nematodes, and prolonged nematode lifespan by 5 d at 2 μM." (PMID 39519665, 2024). "In contrast, patients with ATTR amyloidosis may be given Tafamidis, which stabilizes the transthyretin tetramer and prevents it from dissociating and misfolding." (PMID 38892061, 2024). "However, ATTR CA can also be caused by specific point mutations in the transthyretin (TTR) gene and is then referred to as variant ATTR (ATTRv) amyloidosis." (PMID 38256502, 2024). "Wild-type transthyretin amyloidosis (ATTR) (or senile systemic amyloidosis) is a non-hereditary form of amyloidosis caused by dissociation and misfolding of serum protein transthyretin." (PMID 39445188, 2024). "TTR amyloidosis is a highly debilitating and life-threatening disease." (PMID 38398647, 2024). "Similarly, elderly men with transthyretin (TTR)-related amyloidosis exhibit a higher adjusted prevalence of CTS compared to the general population." (PMID 38248075, 2024). "Conversely, a neutral variant in TTR, p.Gly26Ser (rs1800458), did not exhibit an association with amyloidosis (P = 0.71)." (PMID 38037155, 2023). "Indeed, in the Transthyretin Amyloidosis Outcomes Survey (THAOS) Registry, more than one-third of asymptomatic TTR gene mutation carriers developed ATTRv amyloidosis within a median of approximately 2 years of enrolment." (PMID 37828588, 2023). "Closely related is wild-type TTR (ATTRw), in which the native TTR protein, particularly in the elderly, can destabilize and reaggregate causing nonfamilial cases of TTR amyloidosis." (PMID 37059440, 2023). "In addition, TTR is frequently modified with many different compounds at Cys10 by forming disulfide bonds, which alters the propensity of TTR amyloidosis by modulating TTR stability." (PMID 36835140, 2023). "Similar to the transthyretin amyloidosis trial, interim data show only mild adverse reactions." (PMID 36873375, 2023). "In our study, we have selected a lipid composition that closely resembles that of the first approved and marketed LNP-siRNA drug for targeting hepatocytes in the treatment of polyneuropathy in people with hereditary transthyretin-mediated amyloidosis, a fatal rare disease." (PMID 37514169, 2023). "Normally, TTR can induce amyloidosis by decreasing its thermodynamic and/or kinetic stability." (PMID 36776255, 2023). "Although wild-type transthyretin amyloidosis (ATTRwt) is the most common ATTR-CM, hereditary transthyretin amyloidosis (ATTRv) may also occur." (PMID 38275387, 2023). "We present the case of a patient with TTR amyloidosis, where CCM therapy proved to be effective." (PMID 36769832, 2023). "Additionally, for patients with ATTR amyloidosis, stabilization of the tetrameric transthyretin native state is achieved using small molecule ligands that prevent dissociation, which is a critical first step in amyloid formation." (PMID 37854603, 2023). "All cases were wild-type transthyretin amyloidosis (ATTRwt)." (PMID 36970351, 2023). "Patisiran may not be used in combination with additional ribonucleic acid interfering drugs or transthyretin stabilizers that are used to treat hereditary transthyretin-mediated amyloidosis (hATTR)." (PMID 36835426, 2023).
amyloidosis (continued). "Wild-type transthyretin (ATTRwt) amyloidosis is caused by the misfolding and deposition of the transthyretin protein (TTR) in the absence of mutations in the TTR gene." (PMID 37784196, 2023). "It has been shown that the dissociation of the tetrameric TTR may also cause transthyretin amyloidosis, and the dissociation of the TTR tetramer, required for its amyloid pathogenesis, may be necessary to prevent cellular toxicity from the Aβ oligomers." (PMID 36901707, 2023). "TTR amyloidosis phenotype can be predominantly cardiac, neuropathic, or mixed." (PMID 37926810, 2023). "It has proven efficacy in stabilizing TTR both for Val122Ile mutation and TTRwt amyloidosis without significant adverse effects." (PMID 37288260, 2023). "ATTR-CM is classified into two subtypes according to genetic mutation in the TTR gene: hereditary transthyretin amyloidosis (hATTR), alias ATTR variant, and wild-type transthyretin amyloidosis with no mutation (ATTRwt)." (PMID 37048618, 2023). "More than 100 amyloidogenic TTR mutants lead to the formation of amyloidosis such as familial amyloid polyneuropathy (FAP), familial amyloid cardiomyopathy (FAC) and central nervous system-associated amyloidosis (CNSA), mainly depositing in the heart, lungs and peripheral nerves." (PMID 36835140, 2023). "Both WT-TTR and its more aggressive mutant forms give rise to TTR-related amyloidosis (ATTR)." (PMID 38203650, 2023). "This is likely be due to a stronger cardiotoxic effect of circulating free light chains, promoting a myocarditis-like process, while TTR-related amyloidosis is more akin to a true cardiomyopathy, with longer and less aggressive clinical course despite more impressive phenotypes." (PMID 37115472, 2023). "We present the case of TTR amyloidosis, where CCM therapy proved to be effective." (PMID 36769832, 2023). "For example, patisiran (Onpattro) has been approved by the Food and Drug Administration (FDA) in 2018 as the first lipid nanoparticle-based siRNA drug for the treatment of hereditary transthyretin-mediated amyloidosis, which translates such an idea into the clinical practice." (PMID 37142578, 2023). "In another study, Intellia Therapeutics again developed NTLA‐2001 gene therapy, which is a CRISPR/Cas9 system to knock out the transthyretin (TTR) gene in patients with the progressive, fatal disease hereditary transthyretin amyloidosis, which is caused by mutation of the TTR gene." (PMID 37166046, 2023). "Furthermore, the disease-gene associations related to amyloidosis (Apolipoprotein E [APOE], C3, FGA, Transthyretin [TTR], and Serum amyloid P-component [APCS or SAMP]) showed significant enrichment (FDR = 2.66E-5)." (PMID 37875373, 2023). "The three most frequent types of systemic amyloidosis that may involve the heart are: (i) monoclonal immunoglobulin light-chain (AL) amyloidosis; (ii) hereditary transthyretin (TTR) amyloidosis (ATTRv); and (iii) wild-type TTR amyloidosis (ATTRwt)." (PMID 37892778, 2023). "Amyloid transthyretin (ATTR) amyloidosis is characterized by pathologic accumulation of extracellular protein arising from unstable transthyretin (TTR) tetramers, which dissociate into monomers that misfold, aggregate, and form insoluble fibrils that are resistant to proteolysis." (PMID 37124609, 2023). "The potential of using intravitreal oligonucleotides in ATTRwt amyloidosis might be to specifically inhibit the production of wild-type transthyretin protein in the eye." (PMID 38288300, 2023). "Based on CRISPR/Cas9 technology, Gillmore and colleagues developed a gene editing therapeutic agent named NTLA-2001 that could be the first curative treatment for ATTR (transthyretin) amyloidosis." (PMID 36768539, 2023). "In the case of TTR, PS in the outer membranecan trigger TTR amyloidosis." (PMID 37676231, 2023).
amyloidosis (continued). "Gene therapy can potentially improve the living conditions of affected individuals and is one of the central goals in research on amyloidosis related to the TTR gene, with the advantage of overcoming liver transplantation as the sole treatment for hATTR disease." (PMID 36289657, 2022). "TTR and TTR amyloidosis can potentially activate the coagulation and fibrinolytic systems." (PMID 36224755, 2022). "The 2 main forms of CA are AL and transthyretin (TTR) amyloidosis (ATTR)." (PMID 36606280, 2022). "Hereditary transthyretin (ATTRv) amyloidosis with polyneuropathy, also known as familial amyloid polyneuropathy (FAP), is a severe, progressive, and heterogeneous multisystemic condition due to mutations in the TTR gene." (PMID 36552168, 2022). "The risk of cardiac allograft amyloid recurrence is therefore potentially greater in patients, such as those with ATTRwt-CM, who do not routinely receive TTR suppressing agents." (PMID 36741843, 2022). "Overall, this study suggests that OleA merits consideration for the development of preventives and therapeutics against TTR amyloidosis, contributing to support the importance of a healthy lifestyle, including safe nutrition such as that provided by the Mediterranean diet, rich in plant polyphenols." (PMID 35337074, 2022). "miRNA delivery to the liver is relatively straightforward—for example Patisiran, an siRNA that silences transthyretin in hereditary transthyretin-mediated amyloidosis, is directly delivered to the liver and is the first Food and Drug Administration–approved RNA-based therapy." (PMID 35363256, 2022). "Furthermore, patients affected by symptomatic TTR-amyloidosis showed larger nerve CSA than pre-symptomatic carriers in several nerve sites, more pronounced at brachial plexus." (PMID 36388946, 2022). "The collective message from the in vitro and in vivo studies is thus that Ab-A has the unique dual mode of action of neuroprotection and amyloid debulking, which translates into improvement of the motoric function in a model of neuropathy inducible by human TTR amyloid extract." (PMID 36290413, 2022). "Plasma TTR, mainly synthesized by the liver, forms the fibrils in most hereditary forms of amyloidosis, but wild-type TTR is also amyloidogenic and is the fibril protein in the age-associated wild-type (ATTRwt) amyloidosis, earlier called senile systemic amyloidosis." (PMID 36337276, 2022). "Lack of staining or, more frequently, multiple reaction of a single amyloid deposit with various antibodies can occur, especially with anti- TTR, anti-lambda and anti-kappa IgLCs, and even anti-AApoAI; these make it impossible to define amyloidosis type or can pose a problem for interpretation." (PMID 36545023, 2022). "TTR-related familial amyloid polyneuropathy, normally referred to as hereditary amyloidogenic TTR (hATTR) amyloidosis, is an autosomal dominant disorder with a clinical onset usually before the age of 50 years and an overall survival time of less than 10 years if untreated." (PMID 36156600, 2022). "Patisiran (developed by Alnylam with a trading name Onpattro, Cambridge, MA, United state) was the first siRNA used for the treatment of hereditary transthyretin (hATTR) amyloidosis using LNP-based siRNA drug, approved by the U.S. Food and Drug Administration in 2018." (PMID 36432711, 2022). "Special attention is given to techniques for typing amyloid fibril proteins, necessary for the new therapies available today for cardiac transthyretin related amyloidosis and to avoid patients receiving inappropriate chemotherapy in presence of plasma cell dyscrasia unrelated to amyloidosis." (PMID 36545023, 2022). "Numerous therapeutic strategies have been developed to combat these TTR amyloid diseases." (PMID 35626697, 2022).
amyloidosis (continued). "With regard to Alzheimer’s disease in amyloidosis with dementia, reduced TTR levels have been detected in both the cerebrospinal fluid and plasma of patients with Alzheimer’s disease and in subjects with mild cognitive impairment, becoming more pronounced as the disease progresses." (PMID 35402512, 2022). "Therefore, stabilizing TTR tetramer through pharmacological interventions is a promising strategy for treating TTR amyloidoses." (PMID 35784752, 2022). "The liver is the main source of TTR production and liver transplantation has been one of the most effective treatments to reduce TTR synthesis and improve clinical symptoms in patients with hereditary transthyretin amyloidosis." (PMID 36365206, 2022). "TTR has been recognized as the precursor of systemic amyloidosis both in its wild type form, responsible for wild type TTR amyloidosis (ATTRwt), which affects 10–25% of people over 80 years of age, and in its more than 100 variants causing hereditary TTR amyloidosis (ATTRv)." (PMID 36008960, 2022). "Approved by the EMA and FDA in 2019, oral formulations of Tafamidis are employed in the treatment of transthyretin (TTR) amyloidosis in adult patients with early-stage symptomatic polyneuropathy to delay peripheral neurological impairment of TTR familial amyloid polyneuropathy." (PMID 36364244, 2022). "Bone scintigraphy revealed abnormal cardiac tracer uptake consistent with cardiac TTR-amyloidosis, which could be confirmed by endomyocardial biopsy." (PMID 35925120, 2022). "In fact, patients with TTR amyloidosis present higher plasma proteolytic activity." (PMID 36614141, 2022). "We have previously shown that transthyretin (TTR) amyloidosis patients have amyloid fibrils of either of two compositions; type A fibrils consisting of large amounts of C-terminal TTR fragments in addition to full-length TTR, or type B fibrils consisting of only full-length TTR." (PMID 35358243, 2022). "ATTR-PN is characterized by symmetrical length-dependent peripheral neuropathy; depending on the TTR mutation in the case of ATTRv amyloidosis, distal and occasionally proximal limb weakness may be prominent." (PMID 33609196, 2022). "Diagnosis of ATTR‐PN mainly depends on amyloid deposits in the tissues and TTR gene testing." (PMID 35665499, 2022). "To evaluate whether PDIA4 or BiP overexpression similarly reduced amyloidogenic TTR secretion in an amyloid disease relevant cell line, we monitored total and aggregate FTTTRA25T in conditioned media prepared on liver-derived HepG2 cells." (PMID 35626697, 2022). "These values are higher than those reported for drugs used for TTR-amyloidosis such as Tafamidis (4.4 ± 1.3 nM) and Diflunisal (407 ± 35 nM), but this may be not relevant." (PMID 35337074, 2022). "For example, strategies that enhance PDIA4 chaperoning activity could offer new opportunities to preferentially reduce the secretion and toxic aggregation of TTR in the context of TTR amyloid diseases." (PMID 35626697, 2022). "Two patients were diagnosed with confirmed ATTRwt amyloidosis based on endomyocardial and fat pad biopsies showing TTR positive amyloid deposit by IHC and mass spectrometry, respectively, with no TTR mutation." (PMID 36471404, 2022). "For example, the first FDA-approved double-stranded siRNA therapeutics, patisiran (ONPATTROTM), encapsulated in lipid nanoparticles for delivery to hepatocyte, is used to treat the polyneuropathy of hereditary transthyretin (TTR)-mediated amyloidosis (hATTR) in adults." (PMID 36050716, 2022). "Our results define a mechanistic basis to explain the ATF6 activation-dependent reduction in destabilized, amyloidogenic TTR secretion that could be therapeutically accessed to improve treatments of TTR-related amyloid diseases." (PMID 35626697, 2022). "Although the TTR concentrations were negligible in the healthy volunteers, they were correlated with disease progression and urinary albumin concentrations in the ATTRv V50M amyloidosis patients." (PMID 35893595, 2022).